CD4 (CD4 molecule)
Diseases named in the same sentence as CD4 in open-access papers (continued):
Sharing a sentence is not in itself a finding about the gene and the disease.
diarrhoea (19 papers, 2008 to 2025). "Patients with low CD4+ cell counts are at increased risk for chronic diarrhoea and polyparasitic infection." (PMID 37682831, 2023). "This study shows a positive association of low CD4 count with diarrhoea and parasite positivity (both with P value < 0.01)." (PMID 27493988, 2016). "This can be explained by the fact that there will be low opportunity for these parasites to proliferate and cause diarrhoea as the patient’s CD4+T cell count increases." (PMID 23991132, 2013). "The incidence of chronic diarrhea from all causes in patients with CD4 < 200 cells/uL remain unchanged in the post highly active antiretroviral therapy (HAART) era, ranging from 8 to 10.5% per year." (PMID 20181177, 2009). "Thus, the present study has been aimed to elucidate the associations between diarrhoea and CD4 counts and to study the effect of HAART along with management of diarrhoea in HIV positive patients." (PMID 18713475, 2008). "During early disease stages, while CD4+ counts are high and viral loads low, diarrhoea is often related to HIV seroconversion." (PMID 37682831, 2023). "In our previous study, adoptive transfer of intestinal CD25+ CD4+ Treg cells to food-allergic mice suppressed allergic diarrhea, thus emphasizing the critical role of Treg cells in controlling the allergic symptom." (PMID 33299086, 2021). "The first ever measured total CD4+ lymphocyte count in peripheral blood was higher in diarrhoea patients (p = 0.028; n = 138), but there were significantly lower numbers of (first and last measured) naïve CD4+ lymphocytes in patients with diarrhoea (p = 0.009, n = 28 and p = 0.018, n = 28)." (PMID 32849570, 2020). "The density of CD8+ and CD4+ cells tended to decrease with the grade of diarrhoea (respectively, 1531 ± 577 CD8+ cells/mm2 and 709 ± 493 CD4+ cells/mm2 in grade 2 diarrhoea versus 661 ± 389 and 356 ± 216 in grade 3 diarrhoea) but the difference was not statistically significant." (PMID 40769948, 2025). "Here, we characterized acute and convalescent CD4+ T cell responses in children who were hospitalized with rotavirus-positive and rotavirus-negative diarrhoea in Blantyre, Malawi." (PMID 37268634, 2023). "They found that adult PLHIV in the pre-ART era were 2.4 times as likely to suffer from diarrhoea than HIV-uninfected adults and that this increased risk lasted throughout the infection rather than being limited to those with low CD4+ cell counts." (PMID 37682831, 2023). "CD3+ level was 1100 (622–2402 cells/uL), CD4+ level was 247 (359–1519 cells/uL), CD8+ level was normal at 543 (187–781 cell/uL), and NK cell level was mildly decreased at 74 (6–467uL), during an immune workup for recurrent pulmonary infections and chronic diarrhea few years later." (PMID 40140088, 2025). "Moreover, the frequency of TNF-α and/or IFN-γ-producing VP6-specific CD4+ T cells was similar between children presenting with rotavirus-positive diarrhoea compared to rotavirus-negative diarrhoea." (PMID 37268634, 2023). "However, the fact that rotavirus-specific CD4+ T cells were also rarely detected in rotavirus-vaccinated children presenting with rotavirus-negative diarrhoea suggests that this is unlikely to have been the major reason." (PMID 37268634, 2023). "Weight loss, severe bacterial infection (SBI) and diarrhoea were the main single WHO 3 events triggering switch with CD4≥250 cells/mm3 (44%, 43% and 100% respectively), likely reflecting their frequency in adults irrespective of HIV status or CD4." (PMID 23437399, 2013). "Furthermore, the frequency of CD69−IFN-γ+TNF-α+, CD69−IFN-γ−TNF-α+ and CD69−IFN-γ+TNF-α− CD4+ T cells were higher during acute infection compared to the convalescent stage in children with rotavirus-negative diarrhoea (p = 0.0102, p = 0.0157 and p = 0.0346, respectively)." (PMID 37268634, 2023). "The majority of the responding CD4+ T cells were CD69+IFN-γ−TNF-α− in both rotavirus-positive and rotavirus-negative children with diarrhoea at acute and convalescence phases." (PMID 37268634, 2023).
diarrhoea (continued). "Diarrhoea incidence was over-dispersed in both HIV seropositive (α = 0.263; p < 0.0001) and HIV seronegative adults (α = 0.983; p < 0.0001), and in adults with CD4 counts of less than 200 cells/μL (α = 0.48; p = 0.001)." (PMID 19159487, 2009).
Fever (19 papers, 2013 to 2026). Body temperature elevated above the normal range. "Similar patterns of CD25 and CD62L expression on classical swine fever virus-specific CD8α+CD4- T-cells were observed after immunisation with the C-strain live attenuated classical swine fever vaccine." (PMID 35891467, 2022). "Fever and erythema after vaccination and frequencies of CD4+ T cells, CD8+ T cells, and NK cells were examined to assess immunological function." (PMID 25298213, 2014). "Hypothermia instead of fever observed in M.tb-infected KO mice after CD4+ T cell transfer could be due to excessive inflammation." (PMID 34899731, 2021). "Fever was present in 46% (12/26) of the women infected with P. falciparum and having CD4 < 350/mm3 compared to 26% (5/19) of the women infected with P. falciparum and having CD4 ≥ 350/mm3 (p = 0.22, Fisher exact test)." (PMID 24996807, 2014). "Because the MDSC count rapidly increased during the early stage of DF, changes in the numbers of some relevant immune cells, such as CD4+ T, CD8+ T, and Tregs, with fever duration were assessed for in the 5 DF groups with different fever duration." (PMID 31675923, 2019). "Fever (duration, level) correlated with numbers of central memory CD4+ T cells and anti‐S and anti‐RBD, but not anti‐NC antibody levels." (PMID 33128792, 2021). "The results emphasizes the failure of the individuals that have not developed fever to increase the CD4+ T cell population in contrast to the observed in the fever group individuals (p < 0.05, n = 10)." (PMID 29915591, 2018). "Notably, the percentages of IL-2+ and IFN-γ+ CD4+ T cells were significantly higher in the fever-positive donors after the first dose, rather than after the second dose, in both groups." (PMID 37118516, 2023). "Furthermore, the fever-positive group showed higher AIM+ CD4+ T cell frequencies after the first, but not second, dose." (PMID 37118516, 2023). "In deviation with MDA5+DM patients, the age and sex adjusted multivariate analyses showed that fever, increased levels of serum ferritin, ALT, or LDH, lymphocytes subpopulations including CD3+T cells, CD3+CD4+ T cells, CD3+CD8+T cells were not risk factors for RP-ILD in ASS patients." (PMID 35320936, 2022). "Interestingly, the CD4+ population was also significantly higher in the fever group in comparison to the non-infected group (both control group WTR and RTR, respectively, p < 0.05, n = 10)." (PMID 29915591, 2018). "In contrast, the CD4+ T and CD8+ T cell numbers increased with the fever duration, in negative correlation with the MDSC count, indicating that MDSCs might suppress T-cell function." (PMID 31675923, 2019).
hypertriglyceridemia (19 papers, 2012 to 2025). A laboratory test result indicating elevated triglyceride concentration in the blood. "(2023) found that the risk for hypertriglyceridemia was related to both CD4+ count < 200 cells/μL and CD8+ count ≥ 1000 cells/μL in HIV infection." (PMID 39742334, 2024). "In our study, we found that both CD4 < 200 cells/μL and CD8 ≥ 1000 cells/μL were at high risk for hypertriglyceridemia, and the difference was more significant when expressed as the CD4/CD8 ratio." (PMID 36823632, 2023). "Multivariate analysis also showed that baseline CD4/CD8 ratio < 0.20 was a risk factor for hypertriglyceridemia." (PMID 36823632, 2023). "The incidence of hypertriglyceridemia was 19.9/100 and 10.6/100 person-years in patients with CD4/CD8 ratio between 0.20 and 0.59 and those with CD4/CD8 ratio > 0.60, respectively." (PMID 36823632, 2023). "The results showed that BMI, CD4/CD8 ratio, borderline high TG, and cART regimen were independently associated with the occurrence of hypertriglyceridemia." (PMID 36823632, 2023). "Patients with HFE-H63D variant showed more frequently hypertriglyceridemia (p = .023) and those harboring C9ORF72 expansions > 9 repeats had higher CD4+-cell counts (p = .032) and CD4% (p = .041)." (PMID 35353274, 2022). "Although triglycerides were inversely correlated with CD4 count, clinically important hypertriglyceridaemia was uncommon and was found in only 1/406 (0.2%) ART-naïve participant." (PMID 26986065, 2016). "Children with hypertriglyceridemia presented with higher CD4 count (831 [586–1115.2] vs. 660, p = 0.026) and higher levels of triglycerides were also found in children receiving PI therapy (128.5 mg/dl [88.7-196.7] vs. 85 mg/dl [57–167.5], p = 0.022)." (PMID 25880777, 2015). "Furthermore, the differences in the CD4/CD8 ratio were significantly greater, and the baseline CD4/CD8 ratio < 0.20 was a risk factor for hypertriglyceridemia." (PMID 39742334, 2024). "Multiple Cox regression analysis showed that BMI ≥ 24.0 kg/m2, baseline CD4/CD8 ratio < 0.20, borderline high TG at baseline, and the use of the 3TC + AZT + EFV regimen or 3TC + TDF + LPV/r regimen were independent risk factors for hypertriglyceridemia." (PMID 36823632, 2023). "In combination with the associated CD4/CD8 ratio results, the high risk of hypertriglyceridemia may be associated with the low baseline immunity in our patient." (PMID 36823632, 2023). "Other laboratory abnormalities include markedly elevated soluble IL-2 receptor alpha (sIL-2Rα), hypertriglyceridemia, increased lactate dehydrogenase (LDH), and inversion of the CD4/CD8 ratio, which together support a hyperinflammatory state and lymphoproliferative activity." (PMID 40863427, 2025). "To explore whether hypertriglyceridemia affected the response of the patients to HAART, we analyzed the dynamic changes in viral loads and CD4+ T cell counts." (PMID 26166108, 2015). "However, higher levels of CD4+CD45RA+FoxP3low T cells were found in patients with hypertriglyceridemia compared with those without (1.677 ± 4.543 cells/μl vs. 0.693 ± 2.496 cells/μl; p = 0.03)." (PMID 30662367, 2018).
keloid (19 papers, 2020 to 2025). An irregularly shaped, elevated mark on the skin caused by deposits of excessive amounts of collagen during wound healing. "In summary, DCs and CD4+ T cells were associated with fibroblasts at a significantly high proportion in keloid tissue when compared to perilesional or healthy tissue." (PMID 34502327, 2021). "Here, we demonstrate that monocyte-derived inflammatory dendritic cells (CD1a+, CD11c+, CD14+) and activated CD4+ T lymphocytes (CD45 RO+) dominated the immune infiltration in keloids while associating with fibroblasts." (PMID 34502327, 2021). "The inflammatory processes associated with keloid and hypertrophic scarring are believed to result from a complex interplay of factors, including M2 macrophages, lymphocytes with an increased CD4:CD8 ratio, mast cells, fibroblasts, myofibroblasts, and genetic components." (PMID 39860308, 2025). "Usually, most T cells are CD4+ memory T cells, while in keloids, there is a significantly higher proportion of CD8+ resident memory T cells (TRM) that are known to trigger an exaggerated inflammatory response to stimuli." (PMID 41007836, 2025). "In keloids, the accumulation and activity of CD4+ T cells are particularly considered to be closely related to changes in the local microenvironment." (PMID 40718487, 2025). "The IF staining results showed that the proportion of IL-17A+/CD4+ cells was higher in keloids than in the normal controls." (PMID 39872534, 2024). "The number of CD4+IL-17+ T cells was significantly increased in KP PBMCs and keloid lesion-transplanted mice." (PMID 37524866, 2023). "In the future, treatments that adjust the ratio of CD4+:CD8+ T cells are expected to reduce keloids, such as breaking the high CD4+:CD8+ T-cell ratio in keloids." (PMID 37895153, 2023). "In both PDKX model models that were injected with keloid patient (KP) and healthy control (HC) PBMCs, CD4+ T cells were engrafted well." (PMID 37524866, 2023). "The ratio of immune cells was verified by immunohistochemistry, and the results indicated that there were more CD8+ and CD68+ cells and fewer CD4+ cells in the keloid compared to the surrounding normal skin tissue." (PMID 35990663, 2022). "We found that T follicular helper cells, effector memory CD4 T cells, MDSCs, NK T cells, immature DCs, and neutrophils exhibited significant differences between keloid and the normal tissue." (PMID 35719372, 2022). "The ratio of CD4+naïve T cells and proliferating T cells was decreased in keloids compared with adjacent normal skin tissue, and Augur analysis suggested that proliferative T cells were the cell type with the greatest variation." (PMID 35990663, 2022). "Single sample gene set enrichment analysis (ssGSEA) was performed to analyze the GSE145725 dataset and revealed the infiltration of 28 immune cell subpopulations in keloids, with central memory CD4 T cell scoring highest among the immune cells." (PMID 35669563, 2022). "In comparison with normal skin, keloids have a larger number of T cells, a higher CD4/CD8 ratio, and more persistent peripheral blood lymphocytes, which accelerate collagen production by dermal fibroblasts." (PMID 33413286, 2021). "In line with the increased presence of DC in keloid tissue, we recorded higher levels of CD4+ lymphocytes (≈55 cells/mm2; 16.7%)." (PMID 34502327, 2021). "In this study, immuno-infiltration analysis showed significant differences between keloid and normal tissue in CD4+ effector T cells, myeloid-derived suppressor cells, activated dendritic cells, immature dendritic cells, follicular helper T cells, and monocytes." (PMID 38444850, 2024). "The proportion of CD4+ T cells increased significantly in keloids compared to normal scars, suggesting that CD4+ T cells may play an important role in keloid development." (PMID 39872534, 2024).
keloid (continued). "Because CD4+ T cells undergo significant changes in keloids compared to normal scars, and T cells are important for keloid pathogenesis, we next performed unsupervised clustering of all keloid and normal scar T cells." (PMID 39872534, 2024). "We discovered that the infiltration level of T follicular helper cell and Monocyte were significantly higher in the keloid tissue, while Effector memeory CD4 T cell, Immature dendritic cell, MDSC, Natural killer T cell and Neutrophil presented a high level in normal tissue." (PMID 35719372, 2022). "In summary, dermal DCs and CD4+ T cells were the most abundant cell population in keloid tissue." (PMID 34502327, 2021). "In addition, IL-17-producing CD4+pSTAT3 705+ and CD4+pSTAT3 727+ cells were increased in abundance in the perilesional area of keloids." (PMID 31814061, 2020). "Therefore, they inferred that the high CD4+:CD8+ T-cell ratio may keep the keloid in a high inflammatory response condition as in the early phase of acute wound healing." (PMID 37895153, 2023). "Two weeks after the injection of immune cells from keloid patients or healthy controls into NSG mice, we evaluated the engraftment levels of human CD4 T cells." (PMID 37524866, 2023). "The CyTOF data showed that the ratios of CD4+ T cells, CD8+ T cells and NK cells in keloid tissue were significantly different from those in normal dermal skin." (PMID 35082796, 2021). "The results showed that CD4+ T cells, CD8+ T cells and NK cells were abnormal in keloid tissue compared with normal skin tissue." (PMID 35082796, 2021). "The results also showed that the proportion of CD4+ T cells increased significantly in keloids compared to normal scars and healthy skin." (PMID 39872534, 2024). "Thus, there was not just a general increase in T-lymphocytes, but specifically the regulatory and memory T-cells, as well as an increased CD4+:CD8+ ratio in keloids." (PMID 32528951, 2020). "The results identified significant differences in the proportion of eight immune cell types in keloid and non-keloid tissues, namely activated CD4 T cell, activated CD8 T cell, effector memory CD4 T cell, immature dendritic cell, MDSC, monocyte, neutrophil and T follicular helper cell." (PMID 35669563, 2022). "In addition, the CD4+:CD8+ T-cell ratio was high in keloids when compared to normal skin." (PMID 37895153, 2023).
non-alcoholic fatty liver disease (19 papers, 2019 to 2024). "The significance of CD4+ T lymphocytes in tumor regression is particularly noteworthy, and the dysregulation of lipid metabolism leading to the loss of CD4+ T cells in Non-alcoholic fatty liver disease (NAFLD) can expedite the progression of HCC." (PMID 38426090, 2024). "PPARα was reported to mediate the transcription initiation of CPT gene in CD4+ T-cells isolated from Jurkat cell and a murine model of non-alcoholic fatty liver disease (NAFLD, a risk factor of hepatocellular carcinoma) treated with linoleic acid." (PMID 31275326, 2019). "In vivo inhibition of reactive oxygen species (ROS) effectively reversed the decrease in hepatic‐activated CD4+ T cells induced by nonalcoholic fatty liver disease, subsequently delaying the progression of HCC." (PMID 39428564, 2024). "The number of intrahepatic CD4+ T cells is reduced in livers with non-alcoholic fatty liver disease (NAFLD), accelerating hepatocarcinogenesis." (PMID 33668122, 2021). "A role of CD4+ T cells during the progression from nonalcoholic fatty liver disease (NAFLD) to nonalcoholic steatohepatitis (NASH) has been suggested, but which polarization state of these cells characterizes this progression and the development of fibrosis remain unclear." (PMID 36625344, 2023). "It has been observed that CD161-positive CD4+ and CD8+ T cells tend to accumulate in the liver during infections and non-alcoholic fatty liver disease." (PMID 38914941, 2024). "CD4+ and CD8+ T cell infiltration and inflammatory cytokines are also increased in non-alcoholic fatty liver disease (NAFLD) patients." (PMID 33401245, 2020). "In addition, nonalcoholic fatty liver disease, body weight, lean body mass weight, CD3+CD4+ cell count and virus load were all positively correlated with UA levels, while age was negatively correlated with UA levels." (PMID 34794501, 2021).
nonalcoholic steatohepatitis (19 papers, 2014 to 2025). "PD-1+CD4 Tconv were reduced in the circulation of OB-Dys, exhibited an altered migration potential, and were detected in the liver of patients with non-alcoholic steatohepatitis." (PMID 38380252, 2024). "TNFAIP3 is known to promote the survival of CD4 T cells and to ameliorate the severity of nonalcoholic steatohepatitis." (PMID 38116005, 2023). "NAFLD to (nonalcoholic steatohepatitis) NASH progression correlates with a higher frequency of IL-17(+) cells among liver CD4(+) T cells and higher Th17/resting Treg and Th2/resting Treg ratios in the blood." (PMID 36012327, 2022). "Many biomarkers, including LPS and CD4+ counts have been used to quantify microbial/bacterial translocation in various conditions like cirrhosis, ascites, non-alcoholic steatohepatitis (NASH) and HIV/AIDS." (PMID 25133738, 2014). "This pathway deteriorated non-alcoholic steatohepatitis (NASH) through CD4+ T cell recruitment." (PMID 30992469, 2019). "In metabolic disorders such as nonalcoholic steatohepatitis (NASH) and sepsis, NETs promote oxidative phosphorylation (OXPHOS) and cholesterol metabolism in naïve CD4+ T cells, thereby driving the differentiation of FOXP3+ regulatory T cells (Tregs) through TLR4 signaling." (PMID 40442839, 2025). "Since non-alcoholic steatohepatitis (NASH) involves chronic inflammation, and CD4+ T cell infiltration of the liver is characteristic of NASH patients, we established and characterized a humanized mouse model to identify human-specific immune response(s) associated with NAFLD progression." (PMID 33013934, 2020).